IL5 (interleukin 5)
Diseases named in the same sentence as IL5 in open-access papers (continued):
Sharing a sentence is not in itself a finding about the gene and the disease.
eosinophilia (continued). "IL-5 is the major cytokine supporting eosinophilia, responsible for terminal differentiation of human eosinophils, and regulates eosinophil proliferation, differentiation, maturation, migration, and prevention of cellular apoptosis." (PMID 33917396, 2021). "Recently, interest has also focused on type 2 innate lymphoid cells as inducers of eosinophilia through non-IL-5-dependent mechanisms." (PMID 34739571, 2021). "Helminths-driven immune modulation in these conditions included reduced CD3+, CD4+, CD8+, natural killer (NK), CD4+CD25high and IFN-γ responses, but increased eosinophilia, Tregs, IL-4, IL-5 and IL-10 responses." (PMID 34220854, 2021). "Regarding the rodent-specific S. ratti, the depletion of Gr1+ cells or reduction of eosinophilia by IL-5 depletion were shown to increase S. ratti larval numbers in the head at 1.5 days p.i.." (PMID 34475874, 2021). "Upon activation, ILC2s produce IL-5 and IL-13 among others, resulting in type 2 inflammation characterized by eosinophilia, alternative activation of macrophages, type 2 helper T (Th2) cell differentiation and IgE class switching." (PMID 33968080, 2021). "Th2 cytokines are involved in CTCL pathogenesis of pruritus and include IL-4, IL-5 and IL-13, together with eosinophilia and IgE." (PMID 34118946, 2021). "The presence of eosinophilia and high interleukin-5 levels in the BAL were more common in infants with hospitalized RSV-bronchiolitis in comparison to healthy infants." (PMID 34925333, 2021). "CD40 signalling is important for OVA-induced eosinophilia and the production of IL-4, IL-5, and IL-13 in a mouse model of allergic asthma." (PMID 33976586, 2021). "The promotion of eosinophilia involves signaling by IL-3, IL-5, and GM-CSF, of which the receptors share the CSFR2B cytokine receptor common subunit." (PMID 34576313, 2021). "IL-5 produced by lung-derived ILC2s can drive eosinophilia while IL-13 can stimulate hepatic stellate cells and induce upregulation of fibrosis-associated genes including Col1a1, Acta2 and Timp1, thus promoting liver fibrosis." (PMID 34305911, 2021). "Since IL-4, IL-5, and IL-13 promote airway eosinophilia, mucus overproduction and bronchial hyper-responsiveness, it is likely that hBD-2 improves lung resistance indirectly by lowering those cytokines in the lung." (PMID 33717182, 2021). "IL-5 is the most important factor for this process; however, its binding and action can be inhibited by the use of anti-IL-5 to reduce eosinophilia." (PMID 34644737, 2021). "This type 2 immune response in CRSwNP is supported by the elevation of ILC2, the increased presence of tissue eosinophilia, a clear upregulation of IL-4, IL-5, IL-13, and local IgE, and profound tissue eosinophilia independent of atopy." (PMID 35387015, 2021). "Our findings suggest the suppression of IL-5-mediated eosinophilia as an action mechanism of B-cell-depleting therapy in seronegative EGPA myocarditis." (PMID 34640595, 2021). "Cyclosporine, through its effect on interleukin 5 production (essential for the generation of eosinophilia), is particularly promising and an attractive option." (PMID 34575398, 2021). "The degree of eosinophilia and the levels of IL‐5, ROS, and NFκB were significantly increased, whereas the endogenous levels of vitamin E and Nrf2 were decreased in the lung and BALF in the older mice compared to younger mice." (PMID 34089243, 2021). "For A. lumbricoides, total protein extracts reduce IL-5 and eosinophilia and induce IL-10 to protect mice against experimental asthma." (PMID 34413850, 2021). "Murine studies suggest that IL-5 is important in the induction of reactive eosinophilia during allergen provocations and parasitic infections." (PMID 34409272, 2021). "These responses are accompanied with the induction of cytokines such as IL-4, IL-5, IL-13, and enhanced eosinophilia, and IgE responses." (PMID 34368662, 2021).
eosinophilia (continued). "As Il5 mRNA levels were unaffected by Ruxolitinib, yet eosinophilia was greatly reduced in SA+R mice, our observations suggest that both IL-4 and IL-13 drive eosinophilic inflammation in the lung." (PMID 34777398, 2021). "The activity of these cytokines translates into specific pathophysiological phenomena such as fibrosis (TGF-β), activation of B cells and plasma cells to IgG4 production (IL-10, IL-4, IL-5), and eosinophilia (Il-5, Il-4, Il-13)." (PMID 35145508, 2021). "One seronegative endomyocarditis patient had eosinophilia and disease relapse with asthma attack and worsening cardiac insufficiency 24 months after induction, achieving clinical remission under anti-IL-5 therapy." (PMID 34640595, 2021). "These responses are accompanied with the induction of cytokines such as IL-4, IL-5, IL-13, and increased eosinophilia, IgE as well as goblet cell hyperplasia." (PMID 34220854, 2021). "Several asthmatic features, such as airway hyperresponsiveness, eosinophilia, mucin deposition, and IL-5/IL-13 production in the lungs were decreased in the rAAV-CD39-treated mice." (PMID 34201190, 2021). "IL1RL1 is the receptor for interleukin‐33 (IL‐33) which acts as a selective chemoattractant of Th2 cells, and elicits IL5‐dependent eosinophilia." (PMID 33295083, 2021). "Both papain and IL-33 have been shown to induce ILC2-dependent IL-5 and IL-13 production and airway eosinophilia." (PMID 34194431, 2021). "Blood-circulating lymphocytes producing high amounts of IL-5 and correlating with the severity of esophageal tissue eosinophilia have also been described." (PMID 35095572, 2021). "GATA-3 DNAzyme is being explored in other airway diseases such as chronic obstructive pulmonary disease (COPD), where inhalation of 10 mg SB010 bid for 28 days in COPD patients significantly reduced sputum eosinophilia with a trend to lower IL-5 levels." (PMID 33917396, 2021). "Th2 cells are professional producers of key cytokines involved in allergy and type-2 inflammation, including interleukin (IL)-4 and IL-13 which, among other actions, promote BHR and the production of IgE and mucus, as well as IL-5, which promotes eosinophilia." (PMID 34576313, 2021). "Lastly, benralizumab is seemingly more potent than the other anti-IL-5 agents at suppressing airway eosinophilia." (PMID 35126131, 2021). "Type-2 immunity is characterised by interleukin (IL)-4, IL-5 and IL-13, eosinophilia, mucus production, IgE, and alternatively activated macrophages (AAM)." (PMID 32457448, 2021). "Among patients with eosinophilia, monoclonal antibodies, such as anti-IL5, have also been reported to reduce exacerbations in COPD." (PMID 34831485, 2021). "Cytokines secreted by Th2 cells include IL-4, IL-5 and IL-13, which facilitate the isotope switching of antibodies, mucus secretion and eosinophilia." (PMID 34295337, 2021). "DRESS syndrome (Drug Rash with Eosinophilia and Systemic Symptoms) is a severe delayed type IV hypersensitivity drug reaction by T helper cell 2 (Th2) and Interleukin 5 (IL-5) resulting in activation of eosinophils." (PMID 33777581, 2021). "Group 2 innate lymphoid cells (ILCs) are an important source of interleukin-5, contributing to tissue and blood eosinophilia." (PMID 33265990, 2020). "Interleukin 5 (IL-5) and IL-5 receptor alpha subunit (IL-5α) play key roles in eosinophilia maintenance, and relevant therapeutic strategies include the development of antibodies (Abs) against IL-5 or IL-5α to control eosinophilia." (PMID 33488590, 2020). "Our flow cytometry results revealed that the effects of PGT on reducing OVA-induced eosinophilia are closely related with regulating the levels of IL-5 and IL-13 in the lung." (PMID 33374657, 2020). "The Th2 cytokine IL-5 promotes eosinophilia in SS and L-HES, and activation of the IL5 promoter by GATA3 is directly opposed by the transcription factor SATB1." (PMID 32872487, 2020).
eosinophilia (continued). "With anti-IL5 therapy, a reduction in blood eosinophils is achieved, even in those patients who presented persistent eosinophilia under OCS therapy." (PMID 32787967, 2020). "Anti-IL-5 treated papain challenged Rag1−/− and WT mice were unable to induce eosinophilia in the bone marrow and BAL." (PMID 32582171, 2020). "Again, HpARI suppressed type 2 immune responses while HpARI_CCP1/2 increased BAL eosinophilia, IL-5 and IL-13 production." (PMID 32695116, 2020). "Based on reports that human IL-5 is involved in the pathophysiology of eosinophilic inflammation, eosinophilia and eosinophilic inflammation were used with humanized anti-IL-5 antibodies and anti-human IL-5Rα chain antibodies." (PMID 33265990, 2020). "IL-5 and IL-9 are critical for promoting tissue eosinophilia and mast cell hyperplasia, whereas IL- 13 stimulates mucus production by goblet cells and AHR." (PMID 33114551, 2020). "IL-5 is a Th2 cytokine that induces eosinophilia and also promotes immunoglobulin secretion by B cells." (PMID 32634155, 2020). "Eosinophilia is an important but often variable feature of bronchial asthma, which is highly responsive to corticosteroids and anti-IL-5 therapy." (PMID 32328116, 2020). "Airway eosinophilia in asthmatic patients can also arise by in situ differentiation and is driven by the locally elaborated eosinophilopoietic cytokine IL-5." (PMID 33292332, 2020). "We conclude that IL-33 plays important roles for the initiation of bone marrow eosinophilia where IL-33-responsive bone marrow ILC2s contribute to allergen-induced IL-5-dependent eosinophilic inflammation." (PMID 32582171, 2020). "When ISS-ODN was conjugated with Der f dust mite a suppression of allergen-induced eosinophilia, IL-5 was observed along with an increase in IFN-γ and TGF-β." (PMID 33281825, 2020). "Peripheral blood of chronic asthmatic patients shows elevated levels of IL-5- and IL-13- producing ILC2s, which is paralleled in patient airways by increases in IL-33 and eosinophilia." (PMID 32079296, 2020). "The F1 neonates of maternal DEHP-exposed mice developed more severe allergic lung inflammation after OVA sensitization and challenge, including predominant eosinophilia and higher levels of IL-4, IL-5, and IL-13 in the BALFs, than the control F1 neonates." (PMID 33424850, 2020). "During a classic type 2 immune response, IL-4 promotes B cell antibody class switching to immunoglobin E (IgE), IL-5 recruits eosinophilia to the inflammation sites, and IL-13 promotes mucus production and goblet cell hyperplasia." (PMID 33126494, 2020). "To date, the presence and degree of type 2 inflammatory responses, involving eosinophilia and increased levels of the proinflammatory cytokines IL-4, IL-5, and IL-13, have been the focus of asthma research." (PMID 33101299, 2020). "Elevated numbers of Th2 cells, an overproduction of IL-4 and IL-5, and elevated serum IgE as well as eosinophilia were found in some of these patients." (PMID 33126494, 2020). "The cytokine IL-5 promotes eosinophilic inflammation, and we have previously shown that ILC2s and not TH cells produce IL-5 locally in the bone marrow in IL-33-driven eosinophilia." (PMID 32466530, 2020). "L-HES is defined by early and severe eosinophilia secondary to an over proliferation of abnormal, and often clonal, Th2 T-cells secreting the eosinophilopoietic cytokine interleukin-5 (IL-5)." (PMID 32872487, 2020). "As both IL-4, and IL-5 mRNA levels are unaffected by CD2 deficiency, yet eosinophilia was greatly reduced in HDME-treated Cd2−/− mice, our observations highlight the importance of IL-13 as the central regulator of HDME-induced lung inflammation." (PMID 32477356, 2020). "IL-5 and IL-13 have been reported to stimulate eosinophil activation and induce eosinophilia and ciliated epithelial cell hypertrophy in the respiratory tissue." (PMID 32132898, 2020). "Anti-interleukin-5 antibodies reduced blood eosinophilia in 5/5 patients, but clinical responses were disappointing." (PMID 32849632, 2020).
eosinophilia (continued). "As is well known, IL-5 is essential for eosinophil differentiation, and eosinophilia has been observed in various cancers, including CRC, with a controversial prognosis link." (PMID 33488574, 2020). "CRSwNP is a disease of the upper airways characterized by tissue eosinophilia, high IL-5 and IgE, Th2-polarized responses, and an enrichment of ILC2s." (PMID 31089134, 2019). "Various studies showed that IL-5 cytokine plays an important role in the eosinophilia of the respiratory tract." (PMID 31143692, 2019). "Previous work on filariasis showed that parasite growth and fecundity were enhanced by an IL5‐driven eosinophilia (Babayan, Read, Lawrence, Bain, & Allen, 2010)." (PMID 31871660, 2019). "Strong granzyme B+, interferon (IFN)-γ+ CD8+ cytotoxic T cell and circulating regulatory T (Treg) cell responses were noted during allograft rejection, along with significant eosinophilia and elevated serum IL-5 and eotaxin levels." (PMID 31624262, 2019). "We have previously demonstrated that IL-5 production by ILC2 during influenza infection leads to a mild pulmonary eosinophilia during the recovery stage." (PMID 31415658, 2019). "To date, several treatment approaches, including glucocorticoids, myelosuppressive drugs, leukotriene antagonists, tyrosine kinase inhibitors, IFN-α, and anti-IL-5 antibodies, have been described for eosinophilia." (PMID 31712579, 2019). "Oral administration of 100 mg/kg extract caused 86% inhibition of eosinophilia, reduction of TH2 cytokines (IL-4, IL-5, IL-13) and TNF-α level in BALF and decreased serum IgE level in ovalbumin-sensitized mice." (PMID 31275149, 2019). "The mechanism of hypereosinophilia appears a mutation of the gene located on chromosome 5q31-33, the cytokine gene cluster, the same region as genes crucial for eosinophilia—IL-5, IL-3 and GM-CSF." (PMID 31367340, 2019). "Given the potent role for IL-5 in driving eosinophil accumulation, blockade of IL-5 has also been shown to reduce intestinal eosinophilia and modestly ameliorate experimental colitis in some models, yet not in others." (PMID 30930900, 2019). "Previous studies suggest that CRSwNP is usually characterized by type 2 T-helper (TH2) response and tissue eosinophilia with elevated level of IL-5." (PMID 31249603, 2019). "IL-2/JES6-1 immunocomplexes and low-dose IL-2 therapy are also stimulatory for group 2 innate lymphoid cells (ILC2s) that express CD25, which can contribute to IL-5 production and eosinophilia." (PMID 30930900, 2019). "In allergic asthma cases, Th2 cells mainly release prototype cytokines such as interleukin (IL) 4, IL-5 and IL-13, thereby stimulating type 2 immunity, which has high antibody titers and eosinophilia." (PMID 31438916, 2019). "In particular, IL-5 is responsible for airway eosinophilia and bronchial hyperresponsiveness induced by allergen challenge in sensitized guinea pigs." (PMID 31920718, 2019). "Previous experiments suggest that eotaxin and IL-5 act cooperatively in regulating blood and tissue eosinophilia." (PMID 31315623, 2019). "Rebound blood eosinophilia was observed in two-thirds of anti-IL-5-treated patients, but posttreatment nasal polyp scores did not worsen." (PMID 29682504, 2018). "The asthmatic airway epithelium also produced specific cytokines favoring Th2 and/or Th17 cell differentiation, such as IL-33-promoting IL-5 production and eosinophilia." (PMID 30380761, 2018). "A type 2 immune response was associated with exposure, with increased interleukin-4 (IL-4) production, IL-5 transcription, and eosinophilia." (PMID 28993458, 2018). "Th2 cells migrated to the lung secrete the prototypical Th2 type cytokines IL-4, IL-5, and IL-13, resulting in goblet cell hyperplasia, bronchoconstriction, and eosinophilia in the airway." (PMID 29991953, 2018). "The airway epithelium can also produce specific cytokines favoring Th2 and/or Th17 cell differentiation, such as IL-33 promoting IL-5 production and eosinophilia." (PMID 30380761, 2018).
eosinophilia (continued). "In patients with hypereosinophilic syndrome withdrawal of anti-IL-5 therapy led to a rebound of eosinophilia after 60–90 days." (PMID 30021546, 2018). "Corroborating eosinophilic immunity demonstrable in rodent models, clinical studies have identified that interleukin-5, a growth factor supporting eosinophilia, is a correlate of resistance to helminth re-infection." (PMID 29547639, 2018). "A study shows in a model of lung inflammation that key type 2 cytokine IL-4 derived from basophils enhances ILC2 secretion of IL-5 and IL-13, ultimately favoring eosinophilia." (PMID 30524437, 2018). "Of note, similar values of blood eosinophilia are predictors of response to treatment with both anti-IgE and anti-IL-5 mAbs." (PMID 29879991, 2018). "IL-5 drives eosinophilia in lung tissues by enhancing the development of eosinophils in the bone marrow and their recruitment to the lung." (PMID 29593738, 2018). "Increased sputum IL-5 levels (bound to antibody) and eosinophilia were observed as lung function deteriorated, suggesting that mepolizumab prolonged the half-life of biologically active IL-5, resulting in maturation of eosinophil progenitors in the airways." (PMID 29682504, 2018). "IL-33 initiates allergic inflammation by activating innate lymphoid cells type 2 (ILC2s) to produce large amounts of Th2 cytokines IL-5 and IL-13 responsible for eosinophilia and IgE-class switching, respectively." (PMID 29416104, 2018). "Eosinophilic asthma is characterized by Th2 cell activation, IL-4, IL-5, and IL-13 production, high IgE levels and strong eosinophilia." (PMID 30534125, 2018). "Serum IL-4, IL-5, and IL-6 levels increased in the present case when MM developed with eosinophilia, and these cytokines and eosinophils decreased after the treatment of MM." (PMID 30376895, 2018). "Eosinophilia can constitute an expected side effect of certain cytokine therapies (e.g., IL2, GM-CSF) which cause an IL5 surge, whereas in other cases it represents a DHR." (PMID 29619379, 2018). "M. tuberculosis infection inhibited OVA-induced lung allergic responsessuch as eosinophilia, IL-4 and IL-5 production." (PMID 28128217, 2017). "In an animal model, ovariectomized or estradiol antagonist-treated mice developed reduced IL-5 dependent eosinophilia during allergic inflammation." (PMID 28076614, 2017). "These subgroups were different with respect to their expression levels of IL-5 and IL-13 within the airway, airway hyper-responsiveness, IgE, blood and airway eosinophilia, and reticular basement membrane thickness." (PMID 29018800, 2017). "Inhibition of GM-CSF/IL-3/IL-5 signaling by ASOs targeting the βc of their receptors or CCR3 expression in vivo suppressed antigen-induced eosinophilia and AHR in rat models of allergic asthma." (PMID 28106744, 2017). "Data from our group show that removal of the ovaries 7 days before sensitization to OVA significantly inhibited lung eosinophilia and IL-5 levels in lung lavage fluid." (PMID 28959241, 2017). "In the absence of a hematological malignancy, the Th2-type cytokine interleukin-5 (IL-5) is critical for the development of a peripheral eosinophilia whilst B lymphocyte class-switching to IgE synthesis is dependent on the Th2-type cytokines IL-4/IL-13." (PMID 28506264, 2017). "Induction of eosinophilia is due to Type-2 cytokines IL-4 and IL-5 produced by Th2 and ILC2 cells in response to the parasitic infection." (PMID 29163523, 2017). "Nippostrongylus brasiliensis infection takes about 7 days to induce eosinophilia, so IL-5 appeared well after the activation of T cells to MBP." (PMID 29163523, 2017). "We also demonstrated that NJ.1638 mice had diminished eosinophils in the absence of ST2, indicating that IL-33 regulated the capacity of IL-5 to drive eosinophilia." (PMID 28512632, 2017).